TWIST1 (twist family bHLH transcription factor 1)
Diseases named in the same sentence as TWIST1 in open-access papers (continued):
Sharing a sentence is not in itself a finding about the gene and the disease.
colorectal cancer (continued). "We performed a quantitative RT-PCR assay to analyze the mRNA expression of SNAI1 (Snail1), TWIST1 (Twist1), CDH1 (E-cadherin) and CDH2 (N-cadherin) in FFPE tissue samples of colorectal adenomas (n = 41), colorectal cancer (n = 10) and normal colon mucosa (n = 10)." (PMID 23029563, 2012). "Interestingly, in colorectal cancer, a strong positive correlation was observed between the expression of THBS2 and genes encoding the EMT markers N-cadherin, vimentin, TWIST1, and SNAIL, while there was a negative correlation with CDH1." (PMID 39857742, 2025). "However, consistent with experimental data, colorectal cancers showed a moderate negative correlation between Twist1 and MAD2L1—a mitotic spindle assembly checkpoint protein." (PMID 32337580, 2020). "We observed that these primary colorectal cancer (CRC) cells lost expression of the E-cadherin epithelial marker, which was instead expressed in cancer and normal colon mucosa of the same patient, while overexpressed vimentin (mesenchymal marker), Twist1, Snail (EMT markers) and COX2." (PMID 25738332, 2015). "We hypothesize that discrepancies between methylation and expression among patient samples of colorectal cancer may be due to location of TWIST1 stained cells, namely in the tumor stroma, rather than tumor epithelium." (PMID 25528769, 2015). "Here, we demonstrate that Smad1 promotes migration of colorectal cancer (CRC) cells by inducing Snail and Ajuba expression simultaneously, but no apparent effect on Twist1 expression." (PMID 29299158, 2017).
craniosynostosis (57 papers, 2009 to 2026). Craniosynostosis is defined as the premature fusion of one or more cranial sutures leading to secondary distortion of skull shape resulting in skull deformities with a variable presentation. "TWIST1 haploinsufficiency is associated with craniosynostosis in patients with Saethre-Chotzen syndrome." (PMID 40845104, 2025). "The genetic causes of syndromic craniosynostosis also include alterations in the TWIST1, ERF, and EFNB1 genes, which play a specific role in the development of this condition." (PMID 38396475, 2024). "For example, mutations in the TWIST1 gene are associated with Saethre–Chotzen syndrome, one of the syndromes causing craniosynostosis." (PMID 38396475, 2024). "Saethre-Chotzen syndrome (SCS) is one of the most prevalent craniosynostosis, caused by a loss-of-function mutation in the TWIST-1 gene, with current treatment options relying on major invasive transcranial surgery." (PMID 40225751, 2024). "Some regulatory factors and molecular mechanisms are related to craniosynostosis, including the mutation of the TWIST1 gene." (PMID 38369459, 2024). "Heterozygous loss of function of TWIST1 in humans causes Saethre-Chotzen syndrome, which is characterized by craniosynostosis, facial asymmetry, ptosis, strabismus, and distinctive ear appearance." (PMID 35944701, 2022). "Heterozygous loss of function mutations in TWIST1 cause Saethre-Chotzen syndrome, which is characterized by craniosynostosis, facial asymmetry, ptosis, strabismus, and distinctive ear appearance." (PMID 35944701, 2022). "In humans, mutations in TWIST1 cause Saethre-Chotzen syndrome, which is characterized by craniosynostosis and cleft palate, Sweeney-Cox syndrome and Robinow-Sorauf syndrome." (PMID 35781329, 2022). "These Gli1+ cells are integral to suture maintenance and their loss precedes suture fusion in the Twist1+/− mouse model of craniosynostosis." (PMID 35451466, 2022). "The TWIST1 mutations are associated with Saethre-Chotzen syndrome, a rare congenital disorder often with craniosynostosis, hypertelorism, and syndactyly." (PMID 32051525, 2020). "Saethre-Chotzen syndrome (SCS) is a common form of craniosynostosis, caused by TWIST-1 gene mutations." (PMID 33298158, 2020). "It was found that the mutations in FGF receptors FGFR1, FGFR2, and FGFR3 in humans are associated with craniosynostosis, a characteristic phenotype of the Saethre-Chotzen Syndrome caused by dominant loss-of-function TWIST1 mutations." (PMID 24971743, 2014). "Nevertheless contrary to craniosynostosis, the antiosteogenic function of TWIST1 cannot be the only cause of horn abnormalities as attested hereafter." (PMID 21814570, 2011). "These facts suggest that the mechanism causing the scurs phenotype is the same than for craniosynostosis, i.e. TWIST1 haploinsufficiency." (PMID 21814570, 2011). "Given that RUNX2 is required as a master switch for osteoblast differentiation and interacts with TWIST1, mutations in which also cause craniosynostosis, we conclude that the duplication in this family is pathogenic, albeit with reduced penetrance." (PMID 20683987, 2010). "However, Twist1 loss of function in both lineages (neural crest and mesoderm) causes craniosynostosis." (PMID 40845104, 2025). "Mutations and deletions in human TWIST1 are found in patients with the Saethre-Chotzen syndrome, a condition associated with a wide spectrum of craniofacial abnormalities including craniosynostosis, maxillary hypoplasia, narrow palate, facial asymmetry with a deviated nasal septum and cleft palate." (PMID 36768894, 2023). "TWIST1 may affect the transcription of fibroblast growth factor receptors, a gene family implicated in craniosynostosis." (PMID 37761873, 2023). "Similarly, patients with BGS carry mutations in twist family BHLH transcription factor 1 (TWIST1), defects in which are known to cause craniosynostosis." (PMID 33477564, 2021).
craniosynostosis (continued). "Compound heterozygous Twist1(+/-)/Gsk3β(+/-) had a significantly higher frequency of craniosynostosis than predicted by the additive effects of each mutation alone (increasing from 35% in Twist1(+/-) and 15% in Gsk3β(+/-) to 94% in Twist1(+/-)/Gsk3β(+/-) compound heterozygotes)." (PMID 31442251, 2019). "These mouse models demonstrate an increased frequency and severity of craniosynostosis and support the hypothesis that combined dysregulation of the TWIST1 and IGF1 pathways could contribute to an increase risk in humans." (PMID 31442251, 2019). "Saethre‐Chotzen syndrome (SCS), one of the most common forms of syndromic craniosynostosis (premature fusion of the cranial sutures), results from haploinsufficiency of TWIST1, caused by deletions of the entire gene or loss‐of‐function variants within the coding region." (PMID 30040876, 2018). "TWIST1 mutations were some of the first genetic defects linked to craniosynostosis in humans." (PMID 23738319, 2013). "Mutations within TWIST1, a basic-helix-loop-helix transcription factor, result in TWIST1 haploinsufficiency, presenting as unilateral or bilateral coronal suture fusion among other facial malformations in patients with craniosynostosis." (PMID 23738319, 2013). "We used genomic DNA obtained from inbred, randomly selected CS rabbits to determine whether the SNPs we identified in FGFR1, FGFR2, and Twist1 were linked to the presence of craniosynostosis." (PMID 23738319, 2013). "We now report a molecular analysis to determine if four genes implicated in human craniosynostosis, TWIST1 and fibroblast growth factor receptors 1–3 (FGFR1–3), could be the loci of the causative mutation in this unique rabbit model." (PMID 23738319, 2013). "In addition to the FGFR signaling mutations, TWIST1 is implicated in craniosynostosis in humans with Saethre-Chotzen syndrome." (PMID 23738319, 2013). "We used SNP analysis to determine whether FGFR1, FGFR2, or Twist1 were associated with the craniosynostosis phenotype of the rabbit colony." (PMID 23738319, 2013). "Similarly, mutations in TWIST1 cause craniosynostosis, mandibular hypoplasia and cleft palate." (PMID 28769044, 2017). "We generated a miR-200a expression plasmid to test its effectiveness in preventing suture fusion in the Twist1+/− mouse model for craniosynostosis." (PMID 40845104, 2025). "Implanting Gli1+ MSCs and modified GelMA hydrogel into the cranial sutures of craniosynostosis Twist1+/− mice promotes suture regeneration, corrects skull deformities, restores intracranial pressure (ICP), and improves neurocognitive function." (PMID 40723825, 2025). "These in-depth analyses demonstrate that craniosynostosis in the Twist1+/− mice can occur with regions of the suture unfused or in the process of fusing." (PMID 40845104, 2025). "The most prevalent forms of syndromic craniosynostosis include Muenke type (FGFR3 mutations), Saethre-Chotzen type (TWIST1 mutations), Crouzon type (FGFR2 mutations), Pfeiffer type (FGFR1 and FGFR2 mutations), and Apert type (FGFR2 mutations)." (PMID 40723825, 2025). "In short words, this study revealed Periostin/BMP1 axis’s role in coronary craniosynostosis in TWIST1+/− mice by deeply exploring SMSC proliferation and osteogenic differentiation." (PMID 38369459, 2024). "This study explored the Periostin/BMP1 axis in regulating SMSC proliferation and osteogenic differentiation and revealed its effect on craniosynostosis in TWIST1+/− mice." (PMID 38369459, 2024). "In our quest to decode the molecular intricacies behind craniosynostosis in TWIST1+/− mice, we strategically enhanced Periostin expression via targeted adenoviral-mediated overexpression." (PMID 38369459, 2024). "Collectively, these findings not only highlighted the efficacy of Periostin overexpression in mitigating craniosynostosis in TWIST1+/− mice but also underscored the critical involvement of the Periostin/BMP1 axis in craniosynostosis." (PMID 38369459, 2024).
craniosynostosis (continued). "Several rare disorders have been shown to be caused by mutations in TWIST1: Saethre-Chotzen (SCS), Robinow-Sorauf (RSS) and Sweeney-Cox (SwCS) syndromes and Craniosynostosis-1 (CRS1), all presenting with craniosynostosis." (PMID 37761873, 2023). "Genes most commonly mutated in familial craniosynostosis include, besides FGFR2 and FGFR3, the twist family bHLH transcription factor 1 (TWIST1) and ephrin-B1 (EFNB1)." (PMID 37441579, 2023). "EZH2 has also been implicated in premature suture closure in craniosynostosis cases that are accompanied by a mutation in TWIST1, where EZH2 deposits fewer H3K27me3 silencing marks on osteogenic genes when TWIST1 is deleted." (PMID 36982425, 2023). "The loss of the cellular boundary in suture development is another developmental mechanism that contributes to craniosynostosis discovered in Twist1+/− mouse models." (PMID 35451466, 2022). "Some of our mechanistic insights into the etiology of craniosynostosis are derived from Twist1+/− and Fgf gain-of-function mouse models." (PMID 35451466, 2022). "Twist1+/− mice are a well-established model of craniosynostosis in Saethre-Chotzen syndrome and exhibit unilateral or bilateral coronal suture fusion with incomplete penetrance." (PMID 35451466, 2022). "Recent studies have shown that Twist1+/− mice with craniosynostosis also have elevated ICP and multiple neurocognitive behavioral abnormalities, including deficits in sociability, social memory, novel object recognition and motor learning." (PMID 35451466, 2022). "Compound Twist1+/−;Epha4+/− heterozygotes have a more severe craniosynostotic phenotype than single-mutant heterozygous mice, as well as a higher penetrance of craniosynostosis." (PMID 35451466, 2022). "Tcf12 forms a heterodimer with Twist1, and compound heterozygosity generates a more severe craniosynostosis phenotype." (PMID 35451466, 2022). "Crossing Axin2LacZ/+ mouse, endowing enhanced Wnt activation, to a Twist1+/− mouse model of coronal craniosynostosis enriches skeletal stem/progenitor cells in sutures restoring patency." (PMID 34330896, 2021). "Pivotal component mutations in these pathways, including FGFR2 (fibroblast growth factor receptor 2), TWIST1 (twist, drosophila, homolog of 1) and Axin2 (axis inhibitor 2), have been regarded as the origin of craniosynostosis." (PMID 34134783, 2021). "We generated a double transgenic Twist1+/−:Axin2lacZ/+ mouse by crossing Twist1+/− mice (bearing coronal craniosynostosis) with Axin2LacZ/+ mice." (PMID 34330896, 2021). "In this study, we describe the main clinical characteristics of 36 patients with craniosynostosis, as well as some of the pathogenic variants of FGFR1, FGFR2, FGFR3, and TWIST1 genes." (PMID 32510873, 2020). "The suggested genetic causes of craniosynostosis are pathogenic variants in FGFR1, FGFR2, FGFR3, and TWIST1 genes." (PMID 32510873, 2020). "A limited number of single gene mutations are known to cause single-suture craniosynostosis (SSC) (FGFR3, TWIST1, EFNB1 and TCF12), but they are most often associated with syndromic features." (PMID 31442251, 2019). "A genetic cause accounts for ∼25% of craniosynostosis cases, most frequently due to coding mutations in FGFR2, FGFR3, and TWIST1 (Wilkie, Johnson, & Wall, 2017)." (PMID 30040876, 2018). "It has been demonstrated that the stem cell population is diminished in the sutures of Twist1+/− mice with craniosynostosis, which suggests that there is a threshold number of suture stem cells required for maintaining suture patency." (PMID 29665811, 2018). "In order to study related molecules in craniosynostosis, we identified the fact that there is a low expression of periostin in the fusion sutures of craniosynostosis patients and Twist1+/− mice." (PMID 29665811, 2018).
craniosynostosis (continued). "Chromosome conformation capture analyses show that TWIST1 lost genomic interactions with several enhancers due to the chromothripsis event, which likely led to deregulation of TWIST1 expression and contributed to the patient’s craniosynostosis phenotype." (PMID 28126037, 2017). "TWIST1 mutations and deletions (OMIM: 601622) are the main cause of Saethre–Chotzen syndrome (OMIM: 101400), characterized by craniosynostosis and limb abnormalities, including polydactyly, brachydactyly, and syndactyly." (PMID 28126037, 2017). "In particular, when persistent pulmonary hypertension is coupled with craniosynostosis and dysmorphic features, involvement of TWIST1 and PHF14 should be considered." (PMID 28814329, 2017). "Twist1 heterozygotes (Twist1+/-) develop coronal craniosynostosis, owing in part to abberant migration of Wnt-1cre positive cells into the mesodermal compartment of the coronal suture." (PMID 26886780, 2016). "In humans, mutations in the TWIST1 gene are associated with Saethre-Chotzen Syndrome (SCS), which is an autosomal dominant disorder characterized by craniosynostosis, brachydactyly, soft tissue syndactyly and facial dysmorphism." (PMID 24971743, 2014). "It has been proposed that Twist1 haploinsufficiency favors the formation of Twist1 homodimers in the osteogenic front of cranial sutures, which results in the upregulation of Fgfr2 expression and leads to craniosynostosis." (PMID 24971743, 2014). "Twist1 heterozygous knockout mice have been shown to recapitulate the craniosynostosis phenotype of Saethre-Chotzen syndrome." (PMID 23738319, 2013). "Despite its well-known role in craniofacial skeletal development and its causative role in syndromic craniosynostosis, TWIST1 was not implicated by any GWAS of cranial vault dimensions previously." (PMID 40087503, 2025). "The Twist1 heterozygous (Twist1+/−) mice provide an excellent model of craniosynostosis." (PMID 40845104, 2025). "Therefore, we use overexpression of miR-200a to prevent suture fusion in Twist1 mutant mice, a well-known model for craniosynostosis." (PMID 40845104, 2025). "In P21 Twist1+/− mice, the coronal suture is not continuously fused, only specific regions of the suture are fused causing craniosynostosis." (PMID 40845104, 2025). "TWIST1+/− mice have been taken as a representative animal model for craniosynostosis." (PMID 38369459, 2024). "This study aims to further explore the functions and regulatory mechanisms of Periostin and BMP1 in craniosynostosis, analyze the Periostin/BMP1 axis in the proliferation and osteogenic differentiation of SMSCs, and explore its interaction with mutations in the TWIST1 gene." (PMID 38369459, 2024). "This study also found that over-expressing periostin improved craniosynostosis in TWIST1+/− mice." (PMID 38369459, 2024). "Deletions in HDAC9 gene, but not in the TWIST1 protein-coding sequence, caused development of craniosynostosis." (PMID 36795294, 2023). "Mutations in TWIST1 and SPECC1L lead to craniosynostosis and orofacial clefting in humans." (PMID 35781329, 2022). "The population of CD51+;CD200+ cells is also significantly reduced in Twist1+/− mice before suture fusion defects occur, although it remains unknown whether ablation of this cell population leads to craniosynostosis in mice." (PMID 35451466, 2022). "Targeted PCR and Sanger sequencing of FGFR1, FGFR2, FGFR3, TWIST1, and TCF12 genes resulted in the highest diagnostic rate in our cohort of craniosynostosis patients strongly recommend analysing those genes first (isolated CS and syndromic CS without intellectual disability)." (PMID 35591945, 2022). "Collectively, these data support that cWnt activation in the suture mesenchyme of the Twist1+/−:Axin2lacZ/+ COR suture may suppress COR suture craniosynostosis observed in Twist1+/− mice, possibly through expansion of the CD51+;CD200+ cell population." (PMID 34330896, 2021).